BMP15 (bone morphogenetic protein 15)
Diseases named in the same sentence as BMP15 in open-access papers (continued):
Sharing a sentence is not in itself a finding about the gene and the disease.
Primary amenorrhea (4 papers, 2020 to 2025). "Several heterozygous missense BMP15 mutations have been associated with primary amenorrhea, and most are located in the proprotein region." (PMID 39850788, 2025). "We have recently identified a reported heterozygous L148P mutation in BMP15 in 2 sisters with primary amenorrhea." (PMID 39850788, 2025). "The novel C320Y homozygous mutation in human BMP15 is shown to cause primary amenorrhea and OD in human due to aberrant BMP15 signal transductions in GC, which is phenocopied by the ovine animal model." (PMID 39850788, 2025). "Di Pasquale reported the first mutation of BMP15 gene in two sisters with hypergonadotropic ovarian failure characterized by primary amenorrhea and ovarian dysgenesis." (PMID 34187539, 2021). "In C320Y homozygotes, however, BMP15 is predicted to lose dimerization ability into cumulin and therefore cannot activate the receptor, thus producing severe primary amenorrhea and OD." (PMID 39850788, 2025). "A more recent study reported the deletion of both paternal and maternal copies of BMP15 in a 16-year-old patient with primary amenorrhea and FSH levels of 141mIU/ml." (PMID 35232444, 2022). "One woman presenting primary amenorrhea had the p.Gln1177Leu heterozygous missense variant in SMC1B and the p.Ser5Arg heterozygous missense variant in the BMP15 gene." (PMID 33095795, 2020). "In this study, a nonsense homozygous variant (c.343C>T;p.Gln115*) in the BMP15 gene was identified in two siblings (POI-22 and POI-23) with primary amenorrhea." (PMID 33095795, 2020). "The clinical phenotype of primary amenorrhea with reduced ovarian reserve reflected by reduced AMH levels and hypotrophic ovaries is compatible with the known effects of BMP15 on GC proliferation and an arrest in follicle maturation." (PMID 39850788, 2025).
Turner syndrome (4 papers, 2017 to 2025). Turner syndrome is a chromosomal disorder associated with the complete or partial absence of an X chromosome. "Eight TFs and four ERFs are among the differentially expressed genes, as well as eight genes associated with Turner syndrome (PROCR, NR3C1, INSR, APOB, BMP15, F8, IL6, and WAS) and two genes that are haploinsufficient in humans (RAD50 and SLC33A1)." (PMID 28818098, 2017). "When this is the case, the underlying pathogenetic mechanism of follicle depletion are heterogeneous ranging from genetic (Turner’s syndrome, mutations in the genes FMR-1, BMP-15, Foxl2, and recently identified MCM9, SYCE1, STAG3) to auto-immune and iatrogenic causes." (PMID 29176793, 2017). "The existing WT protein does dimerize and bind the receptor with no compromise in folliculogenesis indicating that haploinsufficiency of BMP15 alone is not sufficient explanation for POI in girls with Turner syndrome, as the heterozygous mother in the present study had normal puberty and fertility." (PMID 39850788, 2025).
cyst (3 papers, 2017 to 2022). A sac-like closed membranous structure that may be empty or contain fluid or amorphous material. "Both GDF9 and BMP15, which are representative oocyte secretory factors, are important for cyst breakdown, follicular development, and oocyte maturation." (PMID 35898394, 2022). "Indeed, the formation of multi-oocyte follicles, indicative of the presence of defects in cyst breakdown and oocyte assembly with pre-granulosa cells, has been observed in Bmp15-/- Gdf9+/- mice." (PMID 36249842, 2018).
endometriosis (3 papers, 2023). The growth of functional endometrial tissue in anatomic sites outside the uterine body. "However, until recently, there have not been assay methods available to reliably measure GDF9 or BMP15 in human sera and thus assess if concentrations are altered in patients with endometriosis." (PMID 36380138, 2023). "GDF9 and BMP15 as potential serum biomarkers of oocyte quantity/quality may therefore be altered in patients with endometriosis." (PMID 36380138, 2023). "It is possible that GDF9/BMP15 may be aberrant in specific populations of women with endometriosis, such as has been reported for AMH relative to endometriomas." (PMID 36380138, 2023). "The dilutional effect on GDF9 and BMP15 in serum may be important given that their normal concentration is very low and undetectable in a large proportion of women, potentially affecting the lack difference in the biomarker concentrations detected in women with endometriosis and in controls." (PMID 36380138, 2023). "However, it is unknown if the presence of endometriosis affects serum GDF9 or BMP15." (PMID 36380138, 2023). "For clinical application in reproductive medicine, GDF9 and BMP15 serum biomarker quantitation is unlikely to be aberrant in the presence of endometriosis." (PMID 36380138, 2023). "Together, these results do not demonstrate strong evidence of GDF9 and BMP15 being affected by the presence of endometriosis." (PMID 36380138, 2023). "This study aims to measure serum GDF9/BMP15 in patients with and without endometriosis, to assess whether concentrations are affected by the presence and/or stage of endometriosis, diagnosed by laparoscopic procedures." (PMID 36380138, 2023). "Therefore, for clinical application of GDF9 and BMP15 as potential serum biomarkers in reproductive medicine, quantitation in serum is unlikely to be aberrant due to the presence of endometriosis." (PMID 36380138, 2023).
Obesity (3 papers, 2023 to 2024). Accumulation of substantial excess body fat. "The results of the present study indicate that obesity causes a significant decrease in the serum BMP15 and kisspeptin concentrations in women of reproductive age." (PMID 37790202, 2023). "This study evaluated the impact of obesity on oocyte quality using three main factors that reflect oocyte quality: mtDNA levels in CC, and levels of BMP-15 and HSPG2 in FF." (PMID 39594620, 2024). "This prospective, case-control study evaluated the impact of obesity on oocyte quality based on mtDNA expression in cumulus cells (CC), and on bone morphogenetic protein 15 (BMP-15) and heparan sulfate proteoglycan 2 (HSPG2) in follicular fluid (FF)." (PMID 39594620, 2024). "Obesity appears to reduce the serum BMP15 and kisspeptin concentrations in obese women of reproductive age." (PMID 37790202, 2023). "Thus, the present study sought to determine the effects of obesity on the serum BMP15, GDF9, and kisspeptin concentrations in women of reproductive age." (PMID 37790202, 2023). "In the present study, obesity was found to reduce the BMP15 concentrations in women of reproductive age, and the identified decrease may be one factor leading to reproductive dysfunction in obese women." (PMID 37790202, 2023). "The results of the present study suggested that the BMP15 and kisspeptin concentrations may beassociated with both metabolism and obesity." (PMID 37790202, 2023). "Moreover, obesity may exert detrimental effects on reproduction by decreasing the serum BMP15 and kisspeptin concentrations." (PMID 37790202, 2023). "Obesity can disrupt either the expression or the effect of GDF9 and BMP15 factors, leading to the absence of a correlation between AMH and FSH." (PMID 39457645, 2024).
Premature ovarian insufficiency (3 papers, 2019 to 2023). Amenorrhea due to loss of ovarian function before the age of 40. "In humans, premature ovarian insufficiency is caused by autoimmunity and genetic factors, including mutation of BMP15." (PMID 37992158, 2023). "Here we newly identified p.N103K and p.M184T mutation in the BMP15 gene associated with idiopathic premature ovarian insufficiency." (PMID 35232444, 2022). "In humans, BMP15 gene mutations lead to imperfect protein function and premature ovarian insufficiency." (PMID 35232444, 2022). "Here we investigated the BMP15 gene variants in a population of Iranian women with premature ovarian insufficiency." (PMID 35232444, 2022). "Accordingly, BMP15 has been implicated in the pathophysiology of premature ovarian insufficiency or failure (POI and POF, respectively), which can involve a combination of genetic, endocrine, immune, and environmental factors." (PMID 37992158, 2023).
adenomyosis (2 papers, 2023 to 2024). The growth of endometrial tissue inside the muscular wall of the uterine corpus. "To further investigate how folliculogenesis was impaired in mice affected by adenomyosis, we performed western blot analysis to evaluate the expression of three crucial oocyte-derived factors involved in follicular development: BMP15, FOXL2, and FSHR." (PMID 38451875, 2024). "The reduced expression of critical oocyte-derived factors, including Foxl2, BMP15, and FSHR, further indicates ovarian dysfunction in adenomyosis." (PMID 38451875, 2024). "The protein levels of all these factors were lower in adenomyosis mice compared with control (FOXL2, P = 0.0499; FSHR, P = 0.0044; BMP15, P = 0.0207)." (PMID 38451875, 2024). "The presence of other gynaecological pathogenesis, i.e. adenomyosis (n = 3), endosalpingiosis (n = 1) and leiomyomas (n = 9), did not affect the concentration of GDF9 and BMP15 (data not shown)." (PMID 36380138, 2023).
Zinc deficiency (2 papers, 2024 to 2026). A deficiency of the essential metal Zinc; an essential cofactor for many enzymes. "Gene expression of both an oocyte-specific factor (Bmp15) and granulosa cell-specific factor (Foxl2) shown to regulate nest breakdown was decreased by zinc deficiency (p < 0.05)." (PMID 41677457, 2026). "The mRNA levels of Gdf9 and Bmp15 were down-regulated in zinc deficiency mice, whereas the expression levels of Sohlh and Nobox were remarkably up-regulated." (PMID 38807213, 2024).
idiopathic pulmonary arterial hypertension (1 paper, 2023). A sporadic form of pulmonary arterial hypertension (PAH) characterized by elevated pulmonary arterial resistance leading to right heart failure. "Most BMPR2 variants were reported previously in patients with idiopathic pulmonary arterial hypertension (IPAH), while recent NGS and functional studies have revealed that p.S987F in BMPR2 caused isolated POI by perturbing BMP15/BMPR2/SMAD signaling and GCs proliferation." (PMID 36793102, 2023).
ovarian disorder (1 paper, 2024). A disease involving the ovary. "In female hosts, FMT resulted in a marked reduction in NAM concentration in the blood, and ovarian disorders-including weight reduction, reduced follicle number (mainly PmF), and altered folliculogenesis dynamics-associated with the decrease in AMH, GDF9, BMP15, and MVH proteins." (PMID 38948060, 2024).
ovarian granulosa tumour (1 paper, 2021). A granulosa-stromal cell tumor that arises from the ovary. "In vitro functional study of the novel BMP15 mutation was performed using COV434 (Human ovarian granulosa tumour cells 434) cells of ovarian granulosa, which consistently express BMP responsive element, and luciferase reporter assay." (PMID 34187539, 2021).
persistent Müllerian duct syndrome (1 paper, 2019). "BMP15 was closely related to growth/differentiation factor (GDF) families, BMP families, anti-Müllerian hormone (AMH), and AMH receptor II (AMHR2), which are related to persistent Müllerian duct syndrome, and those proteins were related to the TGF-beta signaling pathway (KEGG)." (PMID 30845640, 2019).
prostate carcinoma (1 paper, 2018). A carcinoma that arises from epithelial cells of the prostate gland. "For exploring the impact of these somatic substitution mutations in the selection region on human cancer, we identified one pathogenic mutation in human BMP4 and one in BMP15, possibly causing prostate cancer and six neutral mutations in BMPs." (PMID 29719616, 2018).
ZIKV infection (1 paper, 2022). "In this study, we found that the significantly decreased mRNA levels of GDF-9, EPAB, and BMP-15 and unaltered AMH after ZIKV infection can impede follicular development to the antral stage." (PMID 34730391, 2022).
cancer (5 papers, 2018 to 2024). A tumor composed of atypical neoplastic, often pleomorphic cells that invade other tissues. "BMP15, OAS1D, OBOX1, and OBOX5 are well-known oocyte-specific growth factors involved in ovarian folliculogenesis and oocyte maturation, and downregulation of their encoding genes has been suggested to compromise fertility in women undergoing cancer treatment." (PMID 33318603, 2020). "Note that BMP15 and INHBA cancers originate in distinct cell types (squamous cells vs epithelial cells, respectively), limiting the relevance of these mutations to understand heterodimerization." (PMID 36214621, 2022). "Interestingly, the expression of each gene in the 10‐gene signature (Bmp15 was not identified) was highly correlated between scaffolds from the 4T07 and 4T1 mice indicating that the previous signature was limited in its ability to delineate metastatic potential of invasive cancer." (PMID 38193115, 2024).
reproductive disease (1 paper, 2019). "Bone morphogenetic protein 15 (BMP15) is strongly associated with animal reproduction and woman reproductive disease." (PMID 31803742, 2019).
BMP15 also shares sentences with these, for which no sentence is quoted: breast carcinoma (3 papers); ovarian hyperstimulation syndrome (3); autoimmune disease (2); autoimmune disorders (2); genetic disorder (2); ovarian dysgenesis (2); tumor (2); acromelic dysplasia (1); Addison's disease (1); amenorrhea (1); autoimmune polyglandular syndrome (1); autoimmune thyroiditis (1); endocrine disorder (1); galactosemia (1); leiomyoma (1); male infertility (1); myasthenia gravis (1); ovarian tumors (1); pituitary deficiency (1); pulmonary arterial hypertension (1); Synthesis (1); systemic lupus erythematosus (1); vitiligo (1).